HGF (hepatocyte growth factor)
Diseases named in the same sentence as HGF in open-access papers (continued):
Sharing a sentence is not in itself a finding about the gene and the disease.
liver fibrosis (continued). "However, the role of NRP-1 in hepatocytes and its potential interaction with HGF/c-Met in exacerbating liver fibrosis remains unknown." (PMID 40419692, 2025). "Studies have shown the overexpression of HGF in BMSCs enhanced the BMSCs’ ability to prevent liver failure and reduce mortality in rats with small-for-size liver grafts as well as enhance their ability to attenuate liver injury in rats with induced liver fibrosis." (PMID 38613627, 2024). "HGF/MET signaling is also necessary for reparative responses, activated upon liver injury, both during hepatocyte-mediated regeneration and liver regeneration associated with HPC expansion and exerts hepatoprotective effects against liver fibrosis through different mechanisms." (PMID 38138981, 2023). "In the rats with liver fibrosis, the HGF/UC‐MSC transplant downregulated the expression of TGF‐β1, Smad2 and Smad3 more efficiently than UC‐MSCs,78 suggesting that the advantageous therapeutic efficacy of HGF/MSCs might depend on the TGF‐β/Smad signalling pathway." (PMID 35922965, 2022). "Therefore, these previous studies possibly support our hypothesis that HGF also plays an important role in the amelioration of liver fibrosis, exerting a protective effect on the intestinal barrier in our NASH model." (PMID 34548598, 2021). "Moreover, RNA-sequencing results showed that HGF was increased in RBPjMF-KO, which validated our previous data that Notch disruption in MFs enhances hepatocyte proliferation via up-regulating the expression of HGF during liver fibrosis regression." (PMID 34239344, 2021). "Moreover, Lgr5+ liver stem cells were isolated from human liver fibrosis tissues, and single human Lgr5+ liver cells expanded as organoids, which could be further enhanced by treatment with HGF and Rspo1 proteins in vitro." (PMID 29079780, 2017). "Taken together, targeting pDsRed2-HGF plasmid-containing vitamin A-liposomes to HSCs entailed raised HGF gene expression and a decline in fibrosis-specific marker proteins and could possibly be optimized to cure liver fibrosis with the help of gene therapy." (PMID 26941644, 2016). "Moreover, HGF also inhibits liver fibrosis and the apoptosis of hepatocytes." (PMID 25501583, 2014). "Furthermore, ASH1 and EZH2 methyltransferases were more repressed in livers of mMMP-9-treated than in livers of HGF-treated animals which may have accounted for the more effective resolution of liver fibrosis in the mMMP-9-treated animal group." (PMID 25380300, 2014). "HGF-induced upregulation of hepatocyte NRP-1, mediated by RARA binding to its promoter, drives liver fibrosis through c-Met pathway activation, highlighting NRP-1 as a potential therapeutic target for liver fibrosis." (PMID 40419692, 2025). "Hepatocyte NRP-1, whose expression is upregulated by HGF by binding the transcription factor RARA to its potential promoter regions, promotes liver fibrosis via the c-Met signaling pathway." (PMID 40419692, 2025). "Thus, Gab1 may affect HGF/c-Met signaling and trigger cell proliferation during liver fibrosis." (PMID 38935609, 2024). "Factors like HGF and/or Rspo1 have been shown to promote expansion of these LGR5 + cells and attenuate liver fibrosis in mice." (PMID 37798809, 2023). "Few AAV-mediated gene therapies were conducted using transgenes hepatocyte growth factor (HGF), bone morphogenetic protein 7 (BMP7), and microRNA-19b (miRNA-19b), where all of them were confirmed to assess the resolution of liver fibrosis." (PMID 37232739, 2023). "EPCs transplantation activated HGF-mediated hepatocyte proliferation and increased sinusoidal blood vessel density by secreting higher MMP-2 and VEGF in carbon tetrachloride-induced liver fibrosis." (PMID 35883127, 2022). "Three-dimensional- (3D-) cultured ADMSCs, which produced high levels of HGF, IGF-1, SDF-1, and other proteins, showed a protective effect on liver fibrosis." (PMID 36248254, 2022).
liver fibrosis (continued). "CYLD controls hepatocyte growth factor (HGF) expression in activated HSCs, which in turn affects liver fibrosis and inflammation." (PMID 35579924, 2022). "Although human platelets secrete less HGF than rodents, TPO receptor agonists stabilize liver functions and reduce liver fibrosis in patients with liver cirrhosis, HCV infection and CLD." (PMID 33803718, 2021). "Our results demonstrate that UDCA can alleviate liver fibrosis in the BDL mice and promote liver regeneration via the ID1‐WNT2/HGF pathway in PH mice." (PMID 33635004, 2021). "Bile duct ligation (BDL) and partial hepatectomy (PH) mouse models were used to verify the effects of UDCA on liver fibrosis, regeneration, and the ID1‐WNT2/HGF pathway." (PMID 33635004, 2021). "HDAC7 is also known to contribute to HSC activation by regulating the expression of hepatocyte growth factor (HGF), inhibiting HSC activation and liver fibrosis." (PMID 33791228, 2021). "HGF-overexpressing ADMSCs significantly decreased the serum levels of ALT and AST, ameliorated radiation-induced liver fibrosis via downregulation of α-SMA and fibronectin, and promoted hepatocyte regeneration." (PMID 31287024, 2019). "HGF plays an important role in the inhibition of ECM accumulation and fibrogenesis in liver fibrosis, which serves as a cytoprotective, regenerative molecule as well as an antifibrotic factor." (PMID 29214887, 2018). "Cut-offs for liver fibrosis (≥F2) were PLGF = 20.20 pg/ml, GDF15 = 1582.76 pg/ml and HGF = 2598.00 pg/ml." (PMID 28301573, 2017). "miR-16 suppresses the expressions of hepatocyte growth factor (HGF) and Smad7 in HCV-induced hepatic fibrosis." (PMID 28680559, 2017). "We established MSCs culture and treated with HGF and FGF4 to increase their repair potential in liver fibrosis." (PMID 25685159, 2015). "The present study was undertaken to examine the possible effects of HGF and FGF4 pretreated MSCs on CCl4 injured hepatocytes and liver fibrosis." (PMID 25685159, 2015). "In this study, we demonstrate that hepatocyte growth factor (HGF), an antifibrotic factor in the process of pulmonary, renal and liver fibrosis, is a negative regulator of cardiac fibroblast transformation in response to transforming growth factor-β1 (TGF-β1)." (PMID 24840640, 2014). "HGF further upregulates NRP-1 through the transcription factor RARA, exacerbating liver fibrosis." (PMID 40419692, 2025). "When comparing the impact of liver fibrosis on patients with and without steatosis on serum growth factor concentrations, the serum level of HGF was increased in advanced fibrosis in patients with steatosis." (PMID 39200991, 2024). "The three-point ligation obstructive cholestasis-induced liver fibrosis rat model was chosen for in vivo evaluation of the hepatoprotective effect of rat ADMSC, rh-HGF, and PRP individually and in combination based on the findings of biochemical, histology, and survival analysis." (PMID 38474368, 2024). "It has been reported that HGF/BM‐MSCs transplantation could upregulate the expression of MMP‐14 and downregulate the expression of the tissue inhibitors of MMP‐1 (TIMP‐1) in the liver fibrosis, whereas BM‐MSCs cannot." (PMID 35922965, 2022). "Moreover, in our work, injection of HGF-induced BMSCs, especially HGF-induced BMSCs silencing lncRNA SNHG1, diminished liver fibrosis to repress cirrhosis in vivo." (PMID 35194023, 2022). "In addition, HD induces secretagogue of adipokines such as adiponectin, leptin, HGF, TNF-α, TGF-β1, and resistin, resulting in liver fibrosis and inflammation." (PMID 34805412, 2021). "In vivo, liver injured tissue promotes inflammatory processes that stimulate MSCs to release various growth factors and cytokines such as HGF, EGF, IL-6 and TNF-α, and among them, HGF plays a well-established role in liver pathogenesis by attenuating liver fibrosis in various in vivo models." (PMID 33466583, 2021).
liver fibrosis (continued). "Previous studies also reported that HGF was more common in the conditioned medium of SHED than in that of BMMSCs and was involved in the protection of the heart from ischemic injury and the resolution of liver fibrosis." (PMID 31771293, 2019). "Growth factors and cytokines within the secretome such as transforming growth factor beta isoform 3 (TGF-β3), hepatocyte growth factor (HGF), IL-10, and tumor necrosis factor-alpha (TNF-α) can modulate cell signaling and processes involved in fibrogenesis and can attenuate liver fibrosis." (PMID 31270691, 2019). "Therefore in the current study, we tested for the first time panel of serum markers of liver fibrosis, including PLGF, GDF15, and HGF." (PMID 28301573, 2017). "This suggests that higher amounts of HGF secretion alone is not sufficient to predict the potency of a particular MSC population to reduce CCl4-induced hepatic fibrosis." (PMID 28610623, 2017). "After hanging drop culture for 1, 2, and 3 days, RT-PCR was used to determine the expression levels of cytokines, including insulin growth factor 1 (IGF-1), interleukin-6 (IL-6), and hepatocyte growth factor (HGF), which play important roles during inhibition of hepatic fibrosis." (PMID 27022400, 2016). "Fibrotic rats only once treated with a plasmid-containing liposomes by means of retrograde intrabiliary infusion exhibited a rise of HGF gene expression and a simultaneous reduction of the fibrotic markers α-SMA, TGF-β1, and collagen type I, resulting in regression of hepatic fibrosis." (PMID 26941644, 2016). "In light of all findings, the current study suggest that OBE can evidently inhibit liver fibrosis, which might be related with attenuating oxidative stress, inhibiting α-SMA production, inducing HGF expression and up-regulating CYP2E1 expression." (PMID 26213907, 2015). "Moreover, the transplantation of HGF and FGF4 pretreated MSCs contributed to the improvement of liver function and in reduction of fibrosis in CCl4-induced mice liver fibrosis." (PMID 25685159, 2015). "Collagen accumulation decreased after 14 days of transplantation and immunohistochemical analysis revealed that the transplanted WJ-MSCs produced albumin, HGF, and metalloproteinase (MMP), suggesting that WJ-MSCs might alleviate liver collagen and could be used in liver fibrosis therapy." (PMID 37440921, 2023). "HGF/MSC administration could induce more HSC apoptosis than MSCs and Ad‐HGF in liver fibrosis." (PMID 35922965, 2022). "Despite the fact that there are promising results regarding the regenerative properties of ADSC or HGF therapy, there are no studies so far that highlight the ability of ADSC and HGF cotreatment to reduce liver fibrosis in the background of pre-existing diabetes." (PMID 36359733, 2022). "Thus, we focused on demonstrating the antifibrotic effect of HGF-based ADSC therapy and establishing the cellular and molecular mechanism by using an in vitro model of activated HSCs, the key player of liver fibrogenesis, and an in vivo model of CCl4-induced liver fibrosis in diabetic mice." (PMID 36359733, 2022). "However, HGF administration could be much more convenient and economical when compared with the HGF-based ADSC therapy and might be of interest for the treatment of liver fibrosis in diabetic patients, consecutive aggression exerts by different environmental factors." (PMID 36359733, 2022). "Of note, the serum concentrations of PLGF, HGF and GDF15 correlated with hepatic fibrosis assessed both non-invasively by TE and semi-quantitatively by liver biopsy." (PMID 28301573, 2017).
pancreatic cancer (115 papers, 2001 to 2026). "Research has linked these genes to apoptosis: HGF inhibits anoikis in pancreatic cancer cells via the PI3K pathway, and MMP13 reduces anoikis through neural/neuroglial antigen 2 (NG2) shedding." (PMID 40014587, 2025). "PAK4 expression is associated with the migration and invasion of pancreatic cancer cells induced by hepatocyte growth factor (HGF)." (PMID 37628845, 2023). "Next, we investigated the underlying mechanisms by which the HGF/c-Met signaling pathway promotes PNI in pancreatic cancer." (PMID 35449152, 2022). "High levels of stromal HGF have been associated with worsened overall survival of pancreatic cancer patients." (PMID 30544501, 2018). "HGF show the functional heterogeneity in tumor-derived human PSCs, which implicated the mitogenic signaling and migration in pancreatic cancer." (PMID 29967585, 2018). "In conclusion, the present study found that the deletion polymorphism of poly(dA) in the HGF promoter was present in various cancer cell lines, including lung, stomach, colorectal and pancreatic cancer, and mesothelioma cell lines." (PMID 25436000, 2015). "In pancreatic tumor samples, the expression of HIF-1α was correlated with upregulation of c-MET and its ligand hepatocyte growth factor (HGF) in both pancreatic cancer cells and stromal cells, and is linked with an increase in lymph node metastases." (PMID 24213498, 2012). "Our findings further show that, in addition to VEGF, CEC levels are strongly associated with the expression levels of IL-8, IL-10, and HGF in pancreatic carcinoma patients." (PMID 22731825, 2012). "HGF has been implicated in the complex interplay between malignant epithelial cells and non-malignant mesenchymal-derived cells residing in the fibro-inflammatory tumor stroma of pancreatic cancers." (PMID 29069737, 2017). "Finally, our study highlights several significant associations between systemic HGF, S1P levels and enhanced egress of BMSCs in patients with pancreatic cancer." (PMID 23672538, 2013). "However, the underlying mechanisms by which the HGF/c-Met pathway promotes PNI in pancreatic cancer remain unknown." (PMID 35449152, 2022). "Combined therapy resulted in a significant therapeutic effect for pancreatic carcinoma orthotopically transplanted into SCID mice engineered to express human HGF." (PMID 40299443, 2025). "Following analysis by orthotopic transplantation of human pancreatic carcinoma in mice engineered to express human HGF revealed significant reduction in metastatic spread, which also suggested the importance of combined therapy in HGF-rich condition." (PMID 40076928, 2025). "It has been shown that serum HGF expression is higher in patients with invasive pancreatic cancer, and overexpression of MET is related to more severe invasion into lymph nodes as well as shorter survival, higher recurrence rates, and later stages of tumors." (PMID 39000029, 2024). "In the context of pancreatic cancer, uPA is particularly significant due to its essential function in activating the HGF/c-MET pathway." (PMID 38473413, 2024). "Other features of the microenvironment in pancreatic cancer with the HGF/c-MET pathway include hypoxia, angiogenesis, metastasis, and the urokinase plasminogen activator positive feed-forward loop." (PMID 38473413, 2024). "Elevated serum HGF levels have been correlated with disease progression in pancreatic cancer patients." (PMID 38473413, 2024). "A study of the human pancreatic cancer cell lines SW1990 and PANC-1 suggested that the binding of HGF and MET causes EMT-associated chemoresistance through its downstream PI3K/Akt pathway." (PMID 39000029, 2024). "Levels of hepatocyte growth factor (HGF) remained unchanged in pancreatic cancer cells grown in irradiated CAF-conditioned medium, but phosphorylation of the HGF receptor was increased in tumor cells cocultured with CAFs." (PMID 37607935, 2023).
pancreatic cancer (continued). "Co-culturing pancreatic cancer cells with irradiated fibroblasts has been shown to significantly enhance cancer cell invasiveness through the activation of the hepatocyte growth factor (HGF)/c-Met signaling pathway." (PMID 37627173, 2023). "KP4 pancreatic cancer cell line was chosen as the signaling sender because it is known to express a high level of HGF and a low level of LIF, which was confirmed by analysis of the CM of KP4 cells." (PMID 37438365, 2023). "CAFs co-cultured with tumor organoids induce EMT and confer gemcitabine resistance to pancreatic cancer cells through hepatocyte growth factor (HGF)." (PMID 37046676, 2023). "In this regard, the HGF/c-MET axis had a vital role in the defense of pancreatic cancer cells against ferroptosis." (PMID 35693705, 2022). "Mechanistically, HGF/c-Met signaling pathway can active the mTOR/NGF axis to promote the PNI of pancreatic cancer." (PMID 35449152, 2022). "The HGF levels in serum have been reported to correlate with pancreatic cancer progression in patients." (PMID 35449152, 2022). "In conclusion, our study has provided evidence supporting that the HGF/c-Met signaling pathway promotes PNI in pancreatic cancer by activating the mTOR/NGF axis and increasing the invasion and migration ability of pancreatic cancer cells." (PMID 35449152, 2022). "Consistent with in vitro results, PSCs and HGF were also involved in pancreatic cancer ferroptosis resistance in vivo." (PMID 35693705, 2022). "Our primary results also implied that the HGF/c-MET axis affects the antioxidant capacity of pancreatic cancer cells and thus the ferroptosis sensitivity of the cells, which is according to a previous publication." (PMID 35693705, 2022). "We also found that compared with the sh mTOR group, activating the HGF/c-Met signaling pathway recovered the N-cadherin and Vimentin expression of pancreatic cancer cells but decreased the E-cadherin expression in the HGF + sh mTOR group." (PMID 35449152, 2022). "We revealed that mTOR is required for the HGF/c-Met signaling pathway to exert its promoting effects on PNI in pancreatic cancer." (PMID 35449152, 2022). "In this study, we further explored the possible mechanism by which the HGF/c-Met pathway promotes PNI in pancreatic cancer." (PMID 35449152, 2022). "Our previous study showed that PSCs facilitate perineural invasion of pancreatic cancer via the HGF/c-Met pathway." (PMID 35449152, 2022). "Erastin and RSL3 induced more c-MET-knockdown pancreatic cancer cell death under coculture conditions or in the presence of HGF." (PMID 35693705, 2022). "The present study aimed to investigate the mechanism that HGF/c-Met pathway facilitates the PNI of pancreatic cancer." (PMID 35449152, 2022). "The MET gene plays an important role in the proliferation and progression of pancreatic cancer through the hepatocyte growth factor (HGF)/C-MET axis." (PMID 35865013, 2022). "The wound healing and Transwell-based assays showed that, compared with the sh mTOR group, HGF recovered the migration and invasion abilities of pancreatic cancer cells in the HGF + sh mTOR group." (PMID 35449152, 2022). "Taken together, our findings suggest a supportive mechanism of the HGF/c-Met signaling pathway in promoting PNI by activating the mTOR/NGF axis in pancreatic cancer." (PMID 35449152, 2022). "The Transwell-based assay showed that activating the HGF/c-Met signaling pathway promotes the migration and invasion abilities of pancreatic cancer cell lines." (PMID 35449152, 2022). "To unveil the signaling pathways sustaining stroma modulation orchestrated by MET activation in the tumor, we analyzed the gene expression profile in pancreatic cancer cells stimulated with HGF and treated with HGF/MET inhibitors." (PMID 34298732, 2021). "The elevated level of HGF in cancer was reported to predict a more aggressive biology in breast, gastric, and pancreatic cancer patients." (PMID 34944713, 2021).